ZFAND2B (zinc finger AN1-type containing 2B)
Description:
Plays a role in protein homeostasis by regulating both the translocation and the ubiquitin-mediated proteasomal degradation of nascent proteins at the endoplasmic reticulum. It is involved in the regulation of signal-mediated translocation of proteins into the endoplasmic reticulum. It also plays a role in the ubiquitin-mediated proteasomal degradation of proteins for which signal-mediated translocation to the endoplasmic reticulum has failed. May therefore function in the endoplasmic reticulum stress-induced pre-emptive quality control, a mechanism that selectively attenuates the translocation of newly synthesized proteins into the endoplasmic reticulum and reroutes them to the cytosol for proteasomal degradation (By similarity). By controlling the steady-state expression of the IGF1R receptor, indirectly regulates the insulin-like growth factor receptor signaling pathway.
Synonyms: AIRAPL
Tractability: PROTAC: ubiquitination databases record sites on it; its protein half-life has been measured.
Gene: Protein-coding gene on chromosome 2 (219,195,237 to 219,209,651, forward strand). Ensembl gene ENSG00000158552.
Subcellular location: Endoplasmic reticulum membrane
Subcellular location (Human Protein Atlas): Nucleoli; Nucleoli rim; Basal body; Cytosol; Nuclear bodies; Nucleoplasm; Primary cilium; Primary cilium tip
Gene Ontology:
Molecular function: K48-linked polyubiquitin modification-dependent protein binding; protein binding; polyubiquitin modification-dependent protein binding; ubiquitin binding; zinc ion binding
Biological process: proteasome-mediated ubiquitin-dependent protein catabolic process; protein targeting to ER; SRP-dependent cotranslational protein targeting to membrane, translocation; regulation of insulin-like growth factor receptor signaling pathway
Cellular component: proteasome complex; endoplasmic reticulum; membrane; endoplasmic reticulum membrane
Genetic constraint (gnomAD): Loss-of-function variants: 27 observed, 40.57 expected, observed/expected ratio (o/e) 0.67, 90% interval 0.49 to 0.92. The upper end of that interval is the gene's LOEUF score, 0.92, which puts it in group 3 of 6, group 1 being the genes least tolerant of losing a copy. Missense variants: 303 observed, 348.63 expected, observed/expected ratio (o/e) 0.87, 90% interval 0.79 to 0.96. Synonymous variants: 111 observed, 126.16 expected, observed/expected ratio (o/e) 0.88, 90% interval 0.75 to 1.03.
Homologues: Orthologues: chimpanzee ZFAND2B (99% identical), macaque ZFAND2B (97% identical), dog ZFAND2B (94% identical), guinea pig ZFAND2B (93% identical), rabbit ZFAND2B (93% identical), pig ZFAND2B (91% identical), mouse Zfand2b (90% identical), rat Zfand2b (86% identical), zebrafish zfand2a (59% identical), Drosophila melanogaster CG12795 (40% identical), Caenorhabditis elegans aip-1 (29% identical). Paralogues in human: ZFAND2A (34% identical), ZFAND1 (24% identical).
Diseases named in the same sentence as ZFAND2B in open-access papers:
ZFAND2B is named in the same sentence as 1 disease in open-access papers, as found by Europe PMC text mining. Sharing a sentence is not in itself a finding about the gene and the disease.
ZFAND2B shares sentences with these, for which no sentence is quoted: myeloproliferative neoplasm (2 papers).